SOX17 (SRY-box transcription factor 17)
Diseases named in the same sentence as SOX17 in open-access papers (continued):
Sharing a sentence is not in itself a finding about the gene and the disease.
cancer (continued). "SOX17 inhibits β-catenin/TCF-dependent transcription and inhibits cancer cell proliferation and colony formation." (PMID 27738313, 2016). "Exosomes were purified from the gastric juice of gastric cancer patients, and the content of cancer-related methylated LINE1 and methylated SOX17 DNA was analyzed by bisulfite pyrosequencing." (PMID 26582468, 2015). "Importantly, the SOXF proteins, namely SOX7, SOX17 and SOX18, were validated to play important roles in cell fate determination and multiple cancer types." (PMID 40778650, 2025). "In these cases, cancer cells ubiquitously showed strong SOX17 immunoreactivity, whereas noncancerous alveolar type II cells did not exhibit significant SOX17 immunoreactivity." (PMID 39385307, 2024). "Further studies could reveal more mechanisms of SOX17's action in CRC and other cancers, potentially leading to breakthroughs in early cancer diagnosis and treatment, ultimately providing patients with more effective therapeutic options." (PMID 39279027, 2024). "Taken together, these data suggested that ZVI@CMC could sensitize ESCC cells to radiation treatment due to recovery of SOX17/NRF2 axis, and combination treatment could serve as a promising strategy to overcome CCRT resistance in SOX17low/NRF2high cancer cells." (PMID 36310172, 2022). "The analyzed genes in this work (SOX17, MYOD1, MAGI2, CDH1, AJAP1, MGMT, CDH13, and RASSF1A) participate in essential biological processes to maintain cell normality, and there is sufficient evidence for their protective role against the development of cancer." (PMID 34991696, 2022). "The SOXF family (SOX7, SOX17 and SOX18) plays a crucial role in angiogenesis or lymphangiogenesis, and SOX18 has been shown to be a potential target for antiangiogenic therapy in cancer." (PMID 32363730, 2020). "Finally, we discovered eight genes (MME, SOX17, AGTR1, PGR, ESR1, PAX8, C3 and IRF6) with high amplification frequency compared to other genes across the cancer types." (PMID 31879572, 2019). "Since APC, FOXA1 and RASSF1A were biomarkers common to BrC, CRC and LC, they were further tested as gene panel for cancer detection (designated “PanCancer”), whereas RARβ2, SCGB3A1, SEPT9 and SOX17 were considered a gene panel for discrimination of primary cancer localization (“CancerType” panel)." (PMID 30261643, 2018). "In addition, studies in Xenopus reported an interaction between beta-catenin and Sox17, promoting expression of Sox17 target genes, and more recently it was suggested that beta-catenin complexes with YAP1 and TBX5 in human cancer cell lines." (PMID 28369070, 2017). "On the other hand, 12 of the NMR-missing genes in this pathway, such as Dkk4, Sox17 and Ccnd3, have not been reported to be related to any disease including cancer." (PMID 24565050, 2013). "The influx of CD8+ T cells through SOX17‐expressing TECs might be independent of TLS in cancer stromal niches." (PMID 39385307, 2024). "Therefore, we hypothesized that SOX17 would transcriptionally down-regulate DNA repair-related genes and damage-responsive genes to sensitize ESCC cells to anti-cancer treatments." (PMID 30777052, 2019). "Interestingly, the transcription factor SOX17, crucial for cell differentiation and development, is absent in several cancers, including cervical squamous cell carcinoma, mesothelioma, and carcinomas of the breast, lung, pancreas, colon, stomach, liver, bladder, and salivary glands." (PMID 39767561, 2024). "Importantly, SOX17 transcriptionally down-regulated DNA repair and damage response-related genes including BRCA1, BRCA2, RAD51, KU80 DNAPK, p21, SIRT1, NFAT5 and REV3L in KYSE510 radio-resistant cells to achieve the sensitization effect to anti-cancer treatment." (PMID 30777052, 2019).
cancer (continued). "Furthermore, our approach identified only genes that are differentially methylated and expressed between cell lines, and not genes that are uniformly suppressed in cancer cells by DNA methylation, such as HIC1 and SOX17, which may be induced by 5AZA." (PMID 25486910, 2014).
adenocarcinoma (3 papers, 2020 to 2024). A common cancer characterized by the presence of malignant glandular cells. "First, SOX17 expression in LUAD cells was limited to non‐mucinous adenocarcinomas in situ." (PMID 39385307, 2024). "SOX17, TAC1, CDO1, HOXA9 and ZFP42 were the 5 genes that were identified in the Cancer Genome Atlas (TCGA) with highly prevalent DNA methylation in lung squamous and adenocarcinoma, but not in normal lung tissue." (PMID 38315228, 2024).
infection (2 papers, 2022 to 2025). The state of being infected such as from the introduction of a foreign agent such as serum, vaccine, antigenic substance or organism. "Thus, activation of WNT signaling by the microenvironment (or in vitro by CHIRON) might be responsible for the stabilization of the SOX17 expression, which is still highly detectable eight days after infection in vitro, or after weeks in vivo." (PMID 40025812, 2025). "As Sox2 and Sox17 are both essential for early development, we conclude that ZIKVUG infection is detrimental to the ICM lineages." (PMID 35900100, 2022).
SOX17 also shares sentences with these, for which no sentence is quoted: choriocarcinoma (2 papers); hematologic malignancies (2); Hepatitis (2); lung squamous cell carcinoma (2); melanoma (2); myocardial infarction (2); oligodendroglioma (2); atrial septal defect (1); bacterial infections (1); bladder cancer (1); bladder tumors (1); cardiovascular diseases (1); Cholecystitis (1); clear cell carcinoma (1); connective tissue disease (1); endometrioid carcinoma (1); epithelial neoplasm (1); female subfertility (1); head and neck cancer (1); hemorrhage (1); hepatoblastoma (1); hypertension (1); insulinoma (1); intestinal cancer (1); intestinal tumours (1); Iron deficiency anemia (1); ischemic stroke (1); leukemia (1); liver cancer (1); male infertility (1).
A further 30 diseases each share a sentence with SOX17 in 1 paper.